LAMP3 (lysosome associated membrane protein 3)
Diseases named in the same sentence as LAMP3 in open-access papers (continued):
Sharing a sentence is not in itself a finding about the gene and the disease.
cancer (continued). "Notably, the proportion of cDC2s exceeds that of cDC1s in tumors, and the abundance of LAMP3+ DCs varies significantly across different cancer types." (PMID 38012715, 2023). "However, the regulatory factors of PD-L1 in LAMP3+ DCs are intricate and display considerable variation among different cancers, despite its upregulation being a common feature in nearly all cancer types." (PMID 38012715, 2023). "In addition, a pluripotent cytokine-interleukin (IL)-15, overexpressed by LAMP3+ DCs, has been reported as an immunotherapeutic agent for the treatment of cancer." (PMID 35831283, 2022). "LAMP3 is rarely expressed in normal cells, but promotes the migration and invasion of cancer cells." (PMID 30344951, 2018). "Moreover, LAMP3 is induced by hypoxic conditions and potentially stimulates hypoxia dependent cancer metastasis." (PMID 30294508, 2018). "LAMP3 is located on chromosome 3q27, a region that is amplified in many types of cancer." (PMID 30344951, 2018). "Our theoretical prediction would be that genes whose expression is affected by perturbation of the gene-driver (i.e. LAMP3) in vitro and correlated to the expression of the gene-driver in the original cancer data should present correlations of the expected sign." (PMID 27737689, 2016). "Two homologs of LAMP3, LAMP1 and LAMP2, have been associated with cancer metastasis previously." (PMID 23294542, 2013). "Recent publications suggest that LAMP3 have metastatic potential in cancers." (PMID 21810281, 2011). "This might be because cancer aggressiveness is increased by the lysosomal release of LAMP3." (PMID 39429383, 2024). "LAMP3 may be a potential biomarker for the survival of cancer patients." (PMID 39429383, 2024). "LAMP3+ cDCs were characterized by high immune regulatory gene expression, including CD274 (encoding PD-L1) and PDCD1LG2 (encoding PD-L2), consistent with “mregDCs,” a subset of DCs co-expressing maturation and immunoregulatory genes identified in various cancers." (PMID 38012392, 2024). "However, in future studies, the use of a larger sample size along with analysis of the overall survival rate and five-year survival rate may yield a more elaborate result and elucidate whether LAMP3 may be a prognostic marker and anti-cancer target in OSCC." (PMID 39429383, 2024). "Furthermore, several immunosuppressive cells were identified to reprogram the metastatic ecosystem, including FOXP3+ regulatory T (Treg) cells, LAMP3+ tolerogenic DCs (tDCs), CCL18+ M2‐like macrophages, RGS5+ cancer‐associated fibroblasts, and LGALS1+ microglial cells." (PMID 36529697, 2023). "Furthermore, LAMP3 is located at chromosome 3q, which is often amplified in cancer tissues." (PMID 26263981, 2015). "It suggested that LAMP3 may be an important molecular marker for prognosis in cancers." (PMID 26263981, 2015). "By evaluating the spatial co-localization patterns of TLS-enriched cell types in other cancer types, we confirmed the co-localization of TLS-enriched cell types including LAMP3+ DC, Treg, plasma cell, and CCL19+ fibroblast across multiple cancer types." (PMID 38744958, 2024). "Top up-regulated genes related to cancer were: (i) IL-20, CLK1, SORBS2, ERG1, PIM1, SNORD3A for normal FHC cells and (ii) TSLP, BHLHA15, LAMP3, ZNF27B, KRT17, ATF3 for cancerous HT29 cells." (PMID 38033043, 2023). "We further identified a DC subset with elevated expression of LAMP3, FSCN1, and CCR7 as migratory DCs (migDCs), as described recently in healthy thymus and various cancer types including breast." (PMID 36609566, 2023). "LAMP3+ DCs has drawn much attention in recent years as an emerging key player in suppressive TME, and have been observed in various types of cancers, which holds potential as novel targets for immunotherapy." (PMID 37957625, 2023).
cancer (continued). "Secretory cDC were transcriptionally identified in cancer and chronic inflammation and phenotypically in HNSCC and corresponded to the mmDC LAMP3+subset." (PMID 35418195, 2022). "For example, LAMP3, which was the most upregulated protein in the HEKn cells transduced with HPV16 E6 and E7, is regarded as a biomarker of several cancers." (PMID 36016386, 2022). "Thus, LAMP3 might serve as a potential molecular marker for the survival of cancer patients." (PMID 28607528, 2017). "LAMP3+ DCs at the invasive margin were also the most abundant in triple-negative tumours; the difference was statistically significant in comparison to luminal/HE2R− (p = 0.02) and luminal/HER2+ (p < 0.001) cancers." (PMID 33919875, 2021). "For LAMP3+ and CD123+ populations, higher cell densities were associated with non-luminal as compared to luminal cancer phenotype." (PMID 33919875, 2021). "For LAMP3+ and CD123+ DCs, higher cell densities were associated with non-luminal as compared to luminal cancer phenotype." (PMID 33919875, 2021). "Importantly, since GATA2 functions upstream of NR3C1 and other enzalutamide-induced cancer-promoting genes (e.g. SLC7A11 and LAMP3), targeting GATA2 maybe a better strategy for improving AR-targeted therapy by enzalutamide." (PMID 31501863, 2019). "Using a previously reported scoring system, we inferred that most LAMP3+ cDCs in TFHL originated from cDC2s, unlike many cancers." (PMID 38012392, 2024).
infection (13 papers, 2011 to 2024). The state of being infected such as from the introduction of a foreign agent such as serum, vaccine, antigenic substance or organism. "We utilized qPCR to determine if LAMP3 expression and viral gene expression were associated early after infection." (PMID 36350153, 2022). "Conversely, the association of LAMP-3 with MbΔp27::p27 was lower than that for infections with MbΔp27 and equivalent to those for infections with either with the double-complemented MbΔp27::p27/p55 strain or the wild-type strain." (PMID 28031264, 2017). "To evaluate the role of Rv2577 in the intracellular trafficking of Mtb in the human THP-1 macrophages, we quantified the association of the late endosomal marker LAMP-3 to the phagosome containing the Mtb wild type, Rv2577 mutant or complemented strains after 3 h of infection." (PMID 33193164, 2020). "In addition, when we analyzed the association of LAMP-3 with the mycobacterial phagosomes after 3 h of infection, the LAMP-3 association with M. smegmatis overexpressing P27 markedly decreased compared to the wild-type strain." (PMID 28031264, 2017). "Infection of LAMP3 KO cells resulted in very little release of HSV-2 by 24 h postinfection compared to WT or OE cells." (PMID 36350153, 2022). "From these data, we conclude that LAMP3 significantly enhances infection and replication of HSV-2 in vaginal epithelial cells." (PMID 36350153, 2022). "The intracellular viral titers confirmed the visual differences seen in HSV-2 GFP imaging and indicated that increased expression of LAMP3 enhanced infection and replication of HSV-2 in VK2 cells." (PMID 36350153, 2022). "This is consistent with LAMP3/CD63’s role shown in previous literature where knockdown of LAMP3/CD63 impeded VSV-LUJV infection of endothelial cells, and LAMP3 knockdown in lung epithelial cells resulted in reduced replication of influenza virus." (PMID 36350153, 2022). "To investigate this, we analyzed the acidification of the M. tuberculosis MtbΔfasR phagosome during infection of human macrophages by staining with Lysotracker dye and measuring the phagosomal acquisition of LAMP-3 (late endosomal/lysosomal markers)." (PMID 33193236, 2020). "After infection, the association of LAMP-3 with MbΔp27::p55 was not significantly different from the MbΔp27 strain." (PMID 28031264, 2017). "To assess if LAMP3 can alter the early phase of infection, we infected WT VK2, LAMP3 OE, and LAMP3 KO cell lines with HSV-2 (MOI of 100)." (PMID 36350153, 2022). "LAMP3/CD63, with other tetraspanins, also alters virus-cell fusion and cell-cell spread of infection." (PMID 36350153, 2022). "We analysed two phagosome markers (LAMP-3 and Cathepsin D) and a marker for autophagy (LC3-II) in macrophages following L. major (GFP-IL81) infection." (PMID 27632901, 2016). "We also transfected the CoV2‐miR‐O7a.2 mimic at a lower concentration to mimic the copy number per cell as observed on the infection (~2,000 copies/cell) (Fig EV5E), and we found that at this concentration as well CoV2‐miR‐O7a.2 is able to downregulate both BATF2 and LAMP3 mRNA (Fig EV5F)." (PMID 34914162, 2022). "We could, for example, verify that expression of IL10 or SOCS3 genes is reduced during the infection or that expression of STAT4, LAMP3, ADORA2A and BIRC3 genes peaks 6 h pi." (PMID 32070192, 2020). "Our results demonstrated that knockdown of LAMP3 did not affect virus entry while attenuated nuclear accumulation of NP at 4 h post-infection." (PMID 21810281, 2011).
immune disease (1 paper, 2025). "The analysis revealed the significant enrichment of genes such as HLA-DQB1, HLA-DPA1, S100A8, SFRP1, CD247, CTSH, and LAMP3, which are linked to inflammatory and immune disease pathways." (PMID 40426861, 2025).
LAMP3 also shares sentences with these, for which no sentence is quoted: prostate carcinoma (4 papers); cutaneous melanoma (3); autoimmune disease (2); bladder cancer (2); breast tumors (2); gastrointestinal tumors (2); head and neck squamous cell carcinoma (2); hepatitis B (2); laryngeal carcinoma (2); oral cancer (2); adenocarcinoma (1); adenoma (1); airway hyperresponsiveness (1); Astrocytoma (1); bronchioloalveolar carcinoma (1); cervix tumors (1); cholangiocarcinoma (1); chordoma (1); Crohn disease (1); cutaneous leishmaniasis (1); cutaneous T-cell lymphoma (1); deficiencies (1); dry eye (1); dysplastic nevi (1); emphysema (1); gastrointestinal stromal tumor (1); glioblastoma (1); heart failure (1); hepatitis C (1); infectious disease (1).
A further 29 diseases each share a sentence with LAMP3 in 1 paper.